RPL19 (ribosomal protein L19)
Diseases named in the same sentence as RPL19 in open-access papers:
RPL19 is named in the same sentence as 32 diseases in open-access papers, as found by Europe PMC text mining. Sharing a sentence is not in itself a finding about the gene and the disease. The quoted sentences say what the papers report.
prostate carcinoma (16 papers, 2011 to 2024). A carcinoma that arises from epithelial cells of the prostate gland. "For example, high RPL19 expression is associated with poor survival in prostate cancer." (PMID 39165691, 2024). "Over-expression of RPL19 is implicated in lower prostate cancer survival." (PMID 30857280, 2019). "RPL19 protein expression was regarded as a prognostic marker for prostate cancer, and fecal RPL19 mRNA was found to be a biomarker for aggressive behavior and is associated with an unfavorable prognosis in colorectal cancer." (PMID 35350574, 2022). "The xenografted tumors with knocked-down RPL19 were significantly smaller than those in the control tumors, and siRNA knockdown of ribosomal protein gene RPL19 abrogates the aggressive phenotype of human prostate cancer." (PMID 35008908, 2022). "RPL19 is upregulated in many prostate cancers, and its downregulation leads to a milder malignant phenotype in vivo, suggesting a functional role in promoting tumorigenesis." (PMID 36733371, 2022). "One study proposed that the expression of RPL19 in malignant prostate cancer cells was significantly higher than that in prostate cells." (PMID 34350180, 2021). "RPL19, which is a tumor-specific antigen of lung adenocarcinoma, can also be used as a prognostic biomarker for prostate cancer, colorectal cancer, and diffuse large B-cell lymphoma." (PMID 34350180, 2021). "To date, increased expression of the rpL19 accurately identifies prostatic malignancy, can discriminate the progressive form of the disease and predicts the biological behavior of individual prostate cancers and patient survival." (PMID 27924828, 2016). "Prostate cancer : The RPL19 gene has been found to be highly overexpressed in prostate cancer cell line." (PMID 22709827, 2012). "For example, RPS3 is involved in the onset of cancer, RPS13 and RPL23 promote the multidrug resistance of gastric cancer cells, and RPL19 is involved in the prognosis of prostate cancer and CRC." (PMID 22272377, 2012). "In prostate cancer, expression of RPL19 is significantly elevated, functionally involved in maintaining the malignant phenotype and hence a potential target for therapeutic intervention." (PMID 21799931, 2011). "Herein we confirm a functional role for RPL19 in promoting the malignant phenotype of human prostate cancer cells." (PMID 21799931, 2011). "The data support the possibility of a functional role for RPL19, acting within a spectrum of altered gene expression, in maintaining the malignant phenotype of human prostate cancer cells." (PMID 21799931, 2011). "We provide novel functional data that posttranscriptional silencing of gene RPL19 using RNAi not only abrogates the malignant phenotype of PC-3M prostate cancer cells but is selective with respect to transcription and translation of other genes." (PMID 21799931, 2011). "This study provides evidence that posttranscriptional silencing of RPL19 using RNAi not only abrogates the malignant phenotype of PC-3M prostate cancer cells but is selective with respect to transcription and translation of other genes." (PMID 21799931, 2011). "Since our initial identification of RPL19 in prostate cancer, its expression has been shown to define poor-prognosis colorectal cancer and as a novel tumor antigen in lung adenocarcinoma." (PMID 21799931, 2011). "As an example, expression of the regulator gene AGR2 we identified to be elevated in prostate cancers of aggressive phenotype was down-regulated ∼11-fold (p<0.02) following RPL19 knockdown." (PMID 21799931, 2011). "RPL19 is also among the few ribosomal protein genes that are up-regulated in embryonic stem cells of human blastocysts and hepatocellular carcinoma, and post-transcriptional silencing of RPL19 alleviates human prostate cancer by controlling the translation of a subset of transcripts." (PMID 39358553, 2024). "RPL19 knockdown reduces growth of human prostate cancer cells both in vitro and as xenografts." (PMID 29954325, 2018).
prostate carcinoma (continued). "Depletion of eL19 (rpL19) suppressed the aggressive phenotype of human prostate cancer." (PMID 28085118, 2017). "Furthermore, siRNA knockdown of RPL19 gene abrogated the aggressive phenotype of human prostate cancer." (PMID 22709827, 2012). "Since elevated RPL19 mRNA occurred as one of a relatively small number of sequences over-expressed in prostate cancer, we hypothesized that its effect was likely to be selective rather than part of a global non-specific elevation in gene expression." (PMID 21799931, 2011). "Furthermore, RPL19 has been proposed to be a sensitive predictor of prostate cancer progression." (PMID 29954325, 2018). "Other ribosomal proteins have been reported in prostate cancer pathogenesis, such as RPL19, RPL21, and RPL24, and have been proposed as good prostate cancer biomarkers." (PMID 36140189, 2022). "In prostate cancer, amplification of erbB2 is infrequent, being reported in only 0.04% to 2% of cases, and therefore not a common mechanism of RPL19 over-expression." (PMID 21799931, 2011).
breast carcinoma (9 papers, 2011 to 2025). "It was reported that RPL19 plays an important role in the progression of hepatocellular carcinoma, lung adenocarcinoma and breast cancer." (PMID 40771929, 2025). "Breast cancers with elevated expression of RPL19 are more sensitive to apoptosis-promoting drugs that induce endoplasmic reticulum stress." (PMID 29530001, 2018). "While enhanced expression of some RP genes has been reported in other human malignancies, including lung, colorectal, prostate and RPL19 in breast cancer this is the first report to define a functional role for RPL19 in the malignant phenotype." (PMID 21799931, 2011). "In a series of human breast cancer biopsies, RPL19 has been reported as being expressed and co-amplified together with ERBB2 and genes PNMT, PSMB3 and NR1D1." (PMID 21799931, 2011). "RPL19 has been identified as a tumor-specific antigen and a prognostic biomarker in breast cancer." (PMID 37426199, 2023). "RPL19 overexpression was reported to induce RES in breast cancer by pre-activation of the UPR." (PMID 36869281, 2023). "Hong, Kim, and Kim have shown that RPL19 is also up-regulated in breast cancer." (PMID 34873618, 2021). "Overexpression of RPL19 has previously been described in a subset of breast cancers." (PMID 29530001, 2018). "CNVs of RPL19 and RPL23 in breast cancer likely occur due to their co-amplification with ERBB2 on 17q12." (PMID 29530001, 2018).
hepatocellular carcinoma (4 papers, 2021 to 2025). A malignant tumor that arises from hepatocytes. "Relationship between RPL19 expression and the clinicopathological features of hepatocellular carcinoma patients." (PMID 34350180, 2021). "Moreover, overexpression of RPL19 predicted a poor prognosis in hepatocellular carcinoma (p < 0.0007)." (PMID 34350180, 2021).
lung carcinoma (3 papers, 2016 to 2021). "Inhibition of RPL19 by siRNA is linked to a regression in lung cancer progression and suppression in cyclinD1 and D3 syntheses." (PMID 34873618, 2021). "Therefore, the decrease in the proliferation of lung cancer cell lines caused by RPL19 knockdown may occur through inhibition of the cell cycle." (PMID 34350180, 2021). "In vitro, RPL19 is overexpressed in lung cancer H1224L cell line and positively correlates with interferon γ (IFN-γ) production." (PMID 34873618, 2021). "It was also found in lung cancer that the level of RPL19 mRNA expression in normal lung tissues was lower than that in lung cancer tissues, and the overexpression RPL19 was positively correlated with interferon IFN-γ." (PMID 34350180, 2021).
colon cancer (2 papers, 2012 to 2021). "RT-PCR has revealed that RPL19 mRNA is up-regulated in late-stage colon cancer cell lines LOVO, Caco-2, HCT 116 and HT29, which indicates that RPL19 could be a prognostic marker in CRC." (PMID 34873618, 2021).
colorectal cancer (2 papers, 2021 to 2022). A primary or metastatic malignant neoplasm that affects the colon or rectum. "Another study showed that the expression of cytokeratin 19 (CK19) and RPL19 in the stool of patients with advanced colorectal cancer was significantly increased." (PMID 34350180, 2021).
COVID-19 (2 papers, 2021 to 2022). A disease caused by infection with severe acute respiratory syndrome coronavirus 2. "However, the COVID-19-related protein RPL19 was negatively correlated with CD14 and B cells naive." (PMID 35720320, 2022).
glioblastoma (2 papers, 2020 to 2022). The most malignant astrocytic tumor (WHO grade IV). "It has been shown that RPL19 is associated with glioblastoma prognosis." (PMID 36733371, 2022).
osteoporosis (2 papers, 2017 to 2022). A condition of reduced bone mass, with decreased cortical thickness and a decrease in the number and size of the trabeculae of cancellous bone (but normal chemical composition), resulting in increased fracture incidence. "Despite OVX with deficient diet, glucocorticoid proved to be the most suitable osteoporosis model in sheep, and it was recommended to test B2M, GAPDH, RPL19, and YWHAZ gene expression that represented standard reference genes for a relative quantification of transcriptional activity of ovine bone." (PMID 36012173, 2022). "Based on our data we recommend testing of B2M, GAPDH, RPL19, and YWHAZ for relative quantification of gene expression studies in ovine bone which it is a robust bio-medical model for evaluating bone-substituents in osteoporosis." (PMID 29258442, 2017).
Alzheimer disease (1 paper, 2025). A progressive, neurodegenerative disease characterized by loss of function and death of nerve cells in several areas of the brain leading to loss of cognitive function such as memory and language. "In contrast, Srsf7 and Rpl19 have been found to be downregulated in microglia in Alzheimer's disease and are associated with homeostatic microglia." (PMID 40045485, 2025).
glioma (1 paper, 2024). A benign or malignant brain and spinal cord tumor that arises from glial cells (astrocytes, oligodendrocytes, ependymal cells). "Of these additional genes, the higher expression of four genes (BMP2, RPL18A, RPL19, and RPS12) was also significantly associated with better survival and delayed tumor recurrence in patients with glioma, especially those with grade III glioma." (PMID 38672212, 2024). "In our study, the overexpression of RPs, such as RPSA, RPL18A, RPL19, and RPS12, was associated with a better prognosis in patients with glioma." (PMID 38672212, 2024). "The higher expression of BMP2, RPL18A, RPL19, and RPS12 is associated with better outcomes in patients with glioma." (PMID 38672212, 2024). "However, the RPs (RPL18A, RPL19, and RPS12) showed a more distinct trend, which was statistically significant for both OS and PFS only in grade III gliomas." (PMID 38672212, 2024).
iron deficiency (1 paper, 2021). "Based on our results, rRNA (Rpl19 and Rps29) are the most stable and highest ranking RG for the weanling model of iron deficiency." (PMID 34600467, 2021). "Based on the ten-selected RG, Rpl19 and Rps29 are the most suitable RG for normalization studies involving gastrocnemius, heart, kidney, liver, lung, and spleen tissues in studies focused on the male weanling model of dietary iron deficiency." (PMID 34600467, 2021).
Nephroblastoma (1 paper, 2025). An embryonal neoplasm characterized by the presence of epithelial, mesenchymal, and blastema components. "In order to confirm the expression of RPL19 in nephroblastoma, 5 paired nephroblastoma tissues and corresponding adjacent samples were collected." (PMID 40771929, 2025). "Induction of cell cycle arrest via autophagy-mediated protein degradation of RPL19 by NVP-BEZ235 effectively suppressed nephroblastoma progression." (PMID 40771929, 2025). "RPL19 was overexpressed in nephroblastoma tissues, and NVPBEZ235 suppressed the expression of RPL19 protein." (PMID 40771929, 2025). "The expression of RPL19 in nephroblastoma tissues and normal tissues was retrieved from the TCGA database." (PMID 40771929, 2025). "Bioinformatics analysis showed that RPL19 levels were much higher in nephroblastoma tissues than in normal samples (P < 0.05)." (PMID 40771929, 2025). "And the qRT-PCR analysis revealed that RPL19 expression was markedly increased in nephroblastoma tissues (P < 0.05)." (PMID 40771929, 2025). "As expected, our data suggested that RPL19 expression was high in nephroblastoma tissues." (PMID 40771929, 2025). "Due to the relationship between ribosomal protein family and PI3K/AKT/mTOR pathway, we hypothesized that NVP-BEZ235 could inhibit nephroblastoma by regulating RPL19." (PMID 40771929, 2025). "Then, we analyzed the expression of RPL19 in nephroblastoma tissues." (PMID 40771929, 2025). "Similarly, western blot results confirmed that RPL19 expression was much higher in nephroblastoma tissues than normal tissues (P < 0.05)." (PMID 40771929, 2025).
Obesity (1 paper, 2023). Accumulation of substantial excess body fat. "Analyzing gene expression on the adipose tissue of mice fed a HD-induced obesity, both RPL19 and cyclophilin A have been suggested the most appropriate reference housekeeping genes." (PMID 37894869, 2023).
prostate tumors (1 paper, 2019). "In fact, significant increase of RPL19 mRNA expression in a substantial number of prostate tumors suggest its importance as a biological marker." (PMID 30972102, 2019).
ZIKV infection (1 paper, 2019). "The effect of RPL19 silencing on viral E protein synthesis was less pronounced upon ZIKV infection than upon YFV or WNV infection." (PMID 30650657, 2019).
cancer (13 papers, 2012 to 2024). A tumor composed of atypical neoplastic, often pleomorphic cells that invade other tissues. "For ERRFI1, RTN4, PHF7, SPRY4, CCND2, and RPL19, H3K36me3 and H3K79me2 enriched higher signals in normal cell lines than that in cancer cells, and the signals of H3K79me2 changed more significantly than H3K36me3 during tumorigenesis." (PMID 37426199, 2023). "Compared with the H3K36me3 signal in RPL19, H3K79me2 enriched more in normal and cancer cell lines." (PMID 37426199, 2023). "RPL19 and RPS3 are both upregulated in high growth situations, specifically in certain cancer cells." (PMID 27830090, 2016). "Examples of RPLs and RPSs include RPL15, RPL19, RPS6 and RPS15A, which have been associated with a negative prognosis in malignant neoplasms of the digestive system." (PMID 38804617, 2024).
tumor (10 papers, 2011 to 2025). "In the in vivo study, NVPBEZ235 significantly inhibited tumor growth in the drug treatment group, while RPL19 overexpression partially counteracted the drug’s effects, promoting tumor growth." (PMID 40771929, 2025). "According to the IHC staining intensity, the expression of the RPL19 protein in tumor tissues was significantly higher than that in paracancerous tissues (P = 0.016)." (PMID 34350180, 2021). "On the contrary, the role of RPL19 in promoting tumor formation was confirmed using transient and stable knockdown of RPL19 mRNA." (PMID 30857280, 2019). "Immunohistochemistry of tumor xenografts detected strong expression of RPL19 protein in both the PC-3Mparental and si-PC-3Mscramble cells." (PMID 21799931, 2011). "Bioinformatic tools were used to evaluate the expression of RPL19 in tumor tissues." (PMID 40771929, 2025). "Our study demonstrates that RPL19 may play an important role in promoting tumor progression and is correlated with a poor prognosis in HCC." (PMID 34350180, 2021). "Knockdown cell lines si-RPL19-PC-3Mclone ST-3 and si-RPL19-PC-3Mclone ST-1 exhibited comparatively little staining, indicating continued suppression of the RPL19 gene in the majority of tumor cells." (PMID 21799931, 2011). "Detection of small amounts of RPL19 protein in some tumor cells is considered to represent clonal variation resulting from continued low-level expression of the gene, rather than its total inhibition, as identified by qPCR of the cells in-vitro and the results of the Western blotting studies." (PMID 21799931, 2011). "RPL19 was speculated to be a prognostic biomarker and promote tumor progression in HCC." (PMID 34350180, 2021). "Using RPL19-TRAPKI-seq, we found that SBF-1 exerts its cytotoxic effects on tumor cells by disturbing cellular oxidative phosphorylation." (PMID 40042546, 2025). "RPL19 knockdown influenced neither proliferation nor apoptosis, but reduced tumor growth via the regulation of cellular adhesion." (PMID 35350574, 2022). "Furthermore, we investigated RPL19 in HCC tissue microarrays and demonstrated that RPL19 was overexpressed in tumor tissues compared with non-tumor tissues (p = 0.016)." (PMID 34350180, 2021). "In the in vivo experiments, three groups were used: NC (negative control) group, drug treatment group, and drug + RPL19 overexpression group, to assess the effect of NVPBEZ235 on tumor growth." (PMID 40771929, 2025).
infection (5 papers, 2019 to 2023). The state of being infected such as from the introduction of a foreign agent such as serum, vaccine, antigenic substance or organism. "In contrast, the biological processes downregulated with infection include ribosomal biogenesis (Rpl3, Rpl37, Rps5, Rpl11, Rplp1, Rpl28, Rpl19, Rps28, Rps14)." (PMID 35789215, 2022). "Flow cytometric analysis performed at 24 h post-infection revealed that silencing of RPL19, RPS3 and DDOST significantly impaired both YFV and WNV replication." (PMID 30650657, 2019). "Finally, at the same post-infection period, the up-regulated transcripts corresponded to RPL19 (28.5%), acidic leucine rich nuclear phosphoprotein 32 (FPN32) (57.1%), and heat shock protein 90 (HSP90) (14.2%)." (PMID 38076451, 2023).
brain disease (1 paper, 2015). "Moreover, 10 genes (ATP1A1, ATP6V1D, C16orf45, CROCC, KLC1, LUC7L2, PIAS2, PRKAR1B, RBFOX1, and RPL19) interacts with at least one brain disease-associated gene." (PMID 26043779, 2015).
RPL19 also shares sentences with these, for which no sentence is quoted: lung adenocarcinoma (2 papers); benign prostatic hyperplasia (1); colon adenocarcinoma (1); Diamond-Blackfan anemia (1); diffuse large B-cell lymphoma (1); gastric cancer (1); liver cancer (1); multiple myeloma (1); myelodysplastic syndrome (1); nematode infections (1); osteosarcoma (1); tick infestation (1).